MPO (myeloperoxidase)
Diseases named in the same sentence as MPO in open-access papers (continued):
Sharing a sentence is not in itself a finding about the gene and the disease.
cyst (4 papers, 2015 to 2025). A sac-like closed membranous structure that may be empty or contain fluid or amorphous material. "Pronounced cyst formation is frequently observed in MPO‐ANCA‐positive interstitial pneumonia; however, the origin and progression of these cystic lesions have not been sufficiently investigated." (PMID 40070290, 2025). "In agreement with previous studies, sitagliptin produced a significant decrease in serum urea, creatinine, MPO, and cyst-C levels while preserving serum albumin compared to the nephrotoxicity group of rats." (PMID 38548778, 2024). "The concentration of macrophage/microglia markers sCD163 and MCP-1 was higher in glioblastoma cyst fluid than in brain abscess pus; lymphocyte marker sCD25 was similar in cyst fluid and pus, whereas neutrophil marker myeloperoxidase was higher in pus." (PMID 35965529, 2022). "Results achieved by the current study also confirmed that CD68+ MΦ and MPO+ neutrophils weakly infiltrate the liver parenchyma surrounding the cyst in chronic infection." (PMID 26578348, 2015).
duodenal ulcer (4 papers, 2021 to 2024). An ulcer in the duodenal wall. "The induction of stress ulcer in the model rats in this study significantly increased MDA and MPO and significantly decreased SOD, GSH-Px, and NO compared with normal, untreated rats." (PMID 33628315, 2021). "Fenchone also displays anti-duodenal ulcer activity, suggesting antioxidant properties akin to those observed in the gastric model, characterized by the restoration of GSH and SOD levels and reductions in MDA and MPO levels." (PMID 38794211, 2024).
encephalitis (4 papers, 2016 to 2024). An acute inflammatory process affecting the brain parenchyma. "MPO may represent a potential biomarker to distinguish encephalitis due to infection versus immune-mediated causes, which may in part relate to neutrophils in the CSF." (PMID 26808276, 2016). "Our study suggests that MPO in the CSF could be explored as a biomarker for a potential infectious aetiology in patients with encephalitis." (PMID 26808276, 2016). "Notably, NMDAR, GAD65, and MPO may be involved not only in acute encephalitis or demyelinating events but also in neurocognitive and psychiatric manifestations, frequently seen in long COVID patients." (PMID 38138047, 2023). "Notably, N-methyl-d-aspartate receptor (NMDAR), glutamic acid decarboxylase 65-kD isoform (GAD65), and myeloperoxidase may be involved not only in acute encephalitis or demyelinating events but also in neurocognitive and psychiatric manifestations, frequently seen in long COVID patients." (PMID 38678084, 2024).
Erythema (4 papers, 2011 to 2023). Redness of the skin, caused by hyperemia of the capillaries in the lower layers of the skin. "EGCG has been found effective against UVB-induced prostaglandin metabolism, and also to reduce UVB-induced erythema, myeloperoxidase activity, hydrogen peroxide generation, and leukocyte infiltration." (PMID 29679037, 2018). "Topical application of GM-1111 significantly decreased phorbol-induced ear edema, MPO activity, increase in erythema, and increase in ear thickness." (PMID 21347371, 2011). "Herein, we report that the topical pre-treatment with FX-cream formulation ameliorated erythema induced by UVB as well as edema and MPO activity, which are important inflammation and neutrophil recruitment parameters." (PMID 30308980, 2018). "Neutrophil (myeloperoxidadse: MPO+) infiltration were substantially observed in the skin sample from the erythema-skewed patients but not in the skin sample from the papulation-skewed patients." (PMID 37783685, 2023). "Intradermal injection of LL-37 into Balb/c mice at four 12-h intervals for 48 h produced cutaneous erythema with central necrosis, prominent intradermal PMN infiltration, marked edema of the dermis and increased tissue myeloperoxidase (MPO) activity." (PMID 21347371, 2011). "The SAGE-containing emollient also significantly reduced the area of erythema and redness score [4.6±0.3 after LL-37 alone, 1.6±0.4 after LL-37+ SAGE (t = 0) and 1.5±0.5 after LL-37+ SAGE (t = 12 h), both P<0.05 vs LL-37 alone], and decreased MPO activity within biopsies of injected skin." (PMID 21347371, 2011).
Fever (4 papers, 2019 to 2023). Body temperature elevated above the normal range. "Importantly, MPO, MMP9 and PRTN3 levels in the placenta associate with self-reported fever in this cohort of parturient women." (PMID 34737733, 2021).
gastric tumors (4 papers, 2016 to 2023). "We found the up-regulation of NETs in gastric tumor by measuring the expression of citH3 and MPO, and these two markers demonstrated the basic morphology and localization of NETs in frozen tumor sections in immunofluorescence analysis." (PMID 37153547, 2023). "The numbers of CD3 (T cells), CD45 (total myeloid cells), F4/80 (macrophages), and myeloperoxidase (MPO) expressing cells (neutrophils) were markedly increased in gastric tumors 3 weeks after GLI2A induction." (PMID 26859571, 2016).
hypercoagulability (4 papers, 2021 to 2025). "Both studies suggested that DNA could predict hypercoagulability, and other NETs biomarkers, such as nucleosomes and MPO-DNA, might be useful to predict CAD progression." (PMID 36224604, 2022).
Hypoalbuminemia (4 papers, 2018 to 2025). The concentration of albumin in the blood circulation is below the lower limit of normal. "In the present study, older age and hypoalbuminemia were significant risk factors for survival of patients with MPO-ANCA-GN." (PMID 33613528, 2020). "Coincidentally, another study conducted in China also found that patients with hypoalbuminemia were at greater risk for ESRD, which may be due to the fact that MPO-ANCA was the main type of AAV and that albumin had an inhibitory effect on the binding between ANCA and its antigen." (PMID 33613528, 2020).
hypothyroidism (4 papers, 2018 to 2025). Abnormally low levels of thyroid hormone. "Prior studies reported an incidence of hypothyroidism ranging from 4% to 20% in AAV patients, and it was strongly associated with positive MPO-ANCA." (PMID 38248799, 2024).
Infertility (4 papers, 2016 to 2023). "In conclusion, our current work showed for the first time the link between stimulated- macrophages and neutrophils, major sources of MPO, and oocyte quality deterioration, highlighting the implications of these cells in infertility caused by inflammatory conditions." (PMID 26982351, 2016). "Although, the association between macrophages and infertility has been repeatedly reported, the current work is the first to mechanistically link the MPO activity with the deterioration in the oocyte quality, which adversely influences infertility." (PMID 26982351, 2016). "Stepwise linear regression analysis revealed that serum MPO/PON ratio levels could significantly predict the duration of infertility (p = 0.012)." (PMID 36836040, 2023). "It revealed that serum MPO/PON ratio could significantly predict the duration of infertility (p = 0.012)." (PMID 36836040, 2023). "A significant direct correlation was observed between serum MPO/PON ratio and the duration of infertility (r = 0.389; p = 0.041)." (PMID 36836040, 2023). "In a cross-sectional study evaluating the levels of ROS in infertile women, inducible nitric oxide synthase (INOS), myeloperoxidase (MPO), and total oxidative status (TOS) were higher compared to healthy fertile women." (PMID 36499748, 2022). "It is unknown whether the association between serum MPO/PON ratio and the duration of infertility is causal or not." (PMID 36836040, 2023). "Moreover, we have also demonstrated that ISO-induced oxidative stress generates inflammation via the upregulation of MPO, TNF-α, and IL-6, which should also contribute to the reduction in testosterone concentrations and the reduced ratio of mature sperm, leading to infertility." (PMID 35326087, 2022).
Kawasaki disease (4 papers, 2019 to 2025). A rare inflammatory disease characterized by an acute febrile, systemic, self-limiting, medium-vessel vasculitis primarily affecting children. "The G allele of the same polymorphism was previously investigated as a genetic marker for Kawasaki disease risk in Taiwanese children and was associated with higher MPO levels." (PMID 40806204, 2025). "MPO showed association with the products of three Kawasaki disease genes (FCGR2A, CASP3, and LTA) and one related to MIS-C (CYBB)." (PMID 36510129, 2022). "Downregulation of MPO expression has been associated with incidence and se-verity of lupus erythematodes, Kawasaki’s disease, inflammatory bowel disease and eosinophilic granulomatosis." (PMID 33916434, 2021).
metastatic disease (4 papers, 2023 to 2025). "Moreover, intraperitoneal administration of P.g. significantly enhanced growth of SCC7-induced tumors, promoted lung metastasis, and increased neutrophil extracellular trap-related markers H3cit and MPO, in both implanted and metastatic tumors." (PMID 40924302, 2025). "Notably, MPO-DNA complexes correlated with cfDNA, CitH3 and MPO levels, particularly in elderly patients and those with metastatic disease, suggesting their potential as a liquid biopsy marker." (PMID 40801632, 2025). "Moreover, three out of the four NET biomarkers (i.e., dsDNA, nucleosomes and MPO-DNA complexes) were increased in elderly patients compared to young patients and in patients with metastatic disease at diagnosis compared to non metastatic patients." (PMID 37705974, 2023). "In comparison with the control group, there was a significant decrease in the positivity rates of Ly6G, MPO, CitH3, and c-FOS in the metastatic tumors of the treatment group." (PMID 40148973, 2025). "In addition, MPO-DNA complexes and nucleosomes correlated with dsDNA, CitH3, MPO and CXCL8 levels and were increased in elderly patients and patients with metastatic disease at diagnosis." (PMID 37705974, 2023). "Moreover, dsDNA, nucleosome and MPO-DNA complex circulating levels were higher in patients with metastatic disease at diagnosis, compared to patients without metastatic disease." (PMID 37705974, 2023).
mononeuritis multiplex (4 papers, 2022 to 2026). "Neurophysiology confirmed mononeuritis multiplex, and further autoimmune testing revealed positive anti-neutrophil cytoplasmic antibodies (P-ANCA) and elevated myeloperoxidase (MPO) antibodies." (PMID 41020021, 2025).
mouth ulcers (4 papers, 2020 to 2024). "PR3-ANCA positive individuals also had 2.6 (95% CI 1.5 to 4.3, p<0.001) times the adjusted odds of mucous membranes/ocular involvement, which was predominantly characterised by the presence of mouth ulcers/granulomata, compared with MPO-ANCA-positive cases." (PMID 38886004, 2024). "Additionally, when MPO-ANCA (or P-ANCA) positivity was included, similarly, oral ulcers (OR 0.066 95% CI 0.005, 0.920) and MPO-ANCA (or P-ANCA) positivity (OR 328.921, 95% CI 66.231, 1633.498) were significantly associated with OS-LN-AAV as well." (PMID 39407892, 2024). "Therefore, the present study attempted to evaluate the effect of ADSCs seeded onto the curcumin-loaded collagen scaffold on experimental oral ulcers using the histological examination as well as tissue MPO, SOD, and IL-1β assessments." (PMID 33489037, 2020). "Fourth, when clinical data at LN diagnosis were compared according to OS-LN-AAV reclassification, ANCA positivity and MPO-ANCA (or P-ANCA) positivity were proven to be favourable for OS-LN-AAV reclassification, whereas oral ulcers were against it." (PMID 39407892, 2024). "The MPO, SOD, and IL-1β activities were measured in the full-thickness excisional biopsies of oral ulcers." (PMID 33489037, 2020). "When patients were compared based on OS-LN AAV reclassification, ANCA positivity and myeloperoxidase-ANCA (or P-ANCA) positivity favoured for OS-LN-AAV reclassification, whereas oral ulcers did not." (PMID 39407892, 2024).
Multiple Organ Failure (4 papers, 2015 to 2025). A progressive condition usually characterized by combined failure of several organs such as the lungs, liver, kidney, along with some clotting mechanisms, usually postinjury or postoperative. "The present study explored the usefulness of the myeloperoxidase index (MPXI) and delta neutrophil index (DNI) as early predictors of multiple organ failure (MOF) after severe trauma." (PMID 40429441, 2025). "Compared with the non-multiple-organ-failure group, the multiple organ failure group had similar myeloperoxidase indices but a significantly higher delta neutrophil index." (PMID 40429441, 2025).
myelodysplastic syndrome (4 papers, 2018 to 2025). A clonal hematopoietic disorder characterized by dysplasia and ineffective hematopoiesis in one or more of the hematopoietic cell lines. "The purpose of the present study was to refine the original gating strategy for quantifying peripheral blood neutrophil MPO expression and to examine the accuracy of the resulting simplified gating strategy in ruling out myelodysplastic syndromes." (PMID 36399441, 2022). "Although flow cytometric analysis of peripheral blood neutrophil myeloperoxidase expression can accurately rule out myelodysplastic neoplasms (MDS), it lacks reliability and efficiency due to the practical limitations of laboratory-developed liquid reagent-based assays." (PMID 40846335, 2025).
myeloid neoplasm (4 papers, 2021 to 2025). Proliferation of myeloid cells originating from a primitive stem cell. "An easy way to identify background MPO deficiency confounding the immunophenotype of a myeloid neoplasm is the MPO expression in background neutrophils gated on the initial flow cytometry." (PMID 38170104, 2023). "Acting as a key player in killing microorganisms within phagocytes, MPO serves as a highly sensitive and specific biomarker for myeloid cells and myeloid tumors." (PMID 40682358, 2025). "Myeloperoxidase (MPO) serves as a highly sensitive and specific marker in myeloid cells and myeloid tumors." (PMID 40682358, 2025). "The IHC revealed that the tumors were positive for myeloperoxidase (MPO++), CD34 (+++), CD43 (+++), CD68 (+), CD117 (+), and Ki67 (40%+), which are markers of myeloid tumors." (PMID 34579724, 2021).
myeloperoxidase deficiency (4 papers, 2019 to 2024). "Our genomic screening showed the presence of a rare pathogenic splicing variant in MPO (c.2031-2A>C), which is responsible for myeloperoxidase deficiency (MPOD)." (PMID 39421445, 2024). "Of note, the c.2031−2A>C change has been previously observed in individuals presenting with myeloperoxidase deficiency (MPOD [MIM: 254600]), an inherited defect of neutrophil microbicidal activity." (PMID 32758448, 2020). "MPO has been reported to be related to myeloperoxidase deficiency (MPOD) that is characterized by decreased myeloperoxidase activity in neutrophils and monocytes that results in disseminated candidiasis." (PMID 31495056, 2019).
Neonatal sepsis (4 papers, 2014 to 2025). Systemic inflammatory response to infection in newborn babies. "AF-MMP-9 (p = 0.006), MPO (p = 0.011), HNE (p = 0.034), and MMP-8/TIMP-1 molar ratio (p = 0.034) were associated with blood culture positive neonatal sepsis when the data were adjusted by gestational age at delivery (data not shown)." (PMID 28167848, 2017).
Obstructive Sleep Apnea (4 papers, 2021 to 2023). "Several observational studies have investigated the association between myeloperoxidase (MPO) and obstructive sleep apnea (OSA)." (PMID 38156091, 2023).
paroxysmal AF (4 papers, 2018 to 2025). "This study demonstrates that plasma MPO levels are higher in persistent AF than in paroxysmal AF and are thus associated with AF progression." (PMID 37719981, 2023). "In patients with paroxysmal AF, elevated plasma MPO levels confer an increased risk of AF recurrence after catheter ablation." (PMID 37719981, 2023). "This study is the first to report that plasma MPO levels were higher in patients with persistent AF than in those with paroxysmal AF; circulating MPO levels were associated with AF progression." (PMID 37719981, 2023). "The percentage of AF recurrence increased stepwise from the lowest to the highest tertiles of plasma MPO levels in both paroxysmal AF and persistent AF." (PMID 37719981, 2023). "The percentage of recurrence increased stepwise with increasing tertiles of MPO levels in both paroxysmal AF and persistent AF." (PMID 37719981, 2023). "Plasma MPO levels were higher in persistent AF than in paroxysmal AF (64.11 [48.65–81.11] vs. 56.31 [40.33–73.51] ng/ml, p = 0.001)." (PMID 37719981, 2023). "MPO levels were higher in persistent AF than in paroxysmal AF and MPO was positively correlated with LAV in AF." (PMID 37719981, 2023). "Plasma MPO levels increased from paroxysmal AF to persistent AF patients (56.31 [40.33–73.51] vs. 64.11 [48.65–81.11] ng/ml, p < 0.001)." (PMID 37719981, 2023). "We found that plasma MPO levels were higher in patients with persistent AF than those with paroxysmal AF." (PMID 37719981, 2023). "Plasma MPO levels were measured in consecutive patients with paroxysmal AF (n = 225) and persistent AF (n = 106)." (PMID 37719981, 2023). "Paatients with paroxysmal AF have less abundant MPO compared to those with persistent and future onset AF." (PMID 37280612, 2023). "In our cohort, higher plasma MPO levels in persistent AF than in paroxysmal AF may indicate that persistent AF presents with more pronounced remodeling and is more refractory." (PMID 37719981, 2023). "Furthermore, plasma MPO levels were positively correlated with LAV in paroxysmal AF and persistent AF." (PMID 37719981, 2023). "A previous study reported no statistical difference in the circulating MPO levels between different AF phenotypes, which is in contrast to our results, probably due to their small sample size (n = 55 for paroxysmal AF; n = 58 for persistent AF)." (PMID 37719981, 2023). "Furthermore, a significant positive correlation was observed between plasma MPO levels and LAV in both AF groups (paroxysmal AF: r = 0.297, p < 0.001; persistent AF: r = 0.311, p < 0.001)." (PMID 37719981, 2023). "MPO aggregations co-localized with fibrofatty strands that penetrated the myocardium in 70% ofpatients with persistent AF, in 33% with paroxysmal AF, in 27% with future onset AF, and in 7% of the non-AF patients (p = 0.01)." (PMID 37280612, 2023).
pneumococcal pneumonia (4 papers, 2010 to 2021). A febrile disease caused by STREPTOCOCCUS PNEUMONIAE. "Although MPO is important for pneumococcal clearance during acute otitis media, the contribution of MPO to host defense against pneumococcal pneumonia is less clear." (PMID 34552589, 2021). "By 16 h following infection, although neutrophil numbers were significantly higher after secondary pneumococcal pneumonia, MPO activity in virus/S." (PMID 24408967, 2014). "Also during pneumococcal pneumonia, the decreased PMN influx most likely caused the decreased MPO and elastase levels." (PMID 30646846, 2019).
psoriatic arthritis (4 papers, 2022 to 2025). Joint inflammation associated with psoriasis. "While this study focuses on psoriatic arthritis, it underscores the broader relevance of MPO as a biomarker in inflammatory conditions, including OA." (PMID 39125536, 2024). "In support of the role for chronic inflammation in the impairment of PMN responses, PMNs isolated from patients with the chronic inflammatory condition psoriatic arthritis had diminished ROS production, phagocytosis, NETosis, and MPO release when stimulated with TNF compared to healthy controls." (PMID 40333334, 2025).